COL1A1 (collagen type I alpha 1 chain)
Diseases named in the same sentence as COL1A1 in open-access papers (continued):
Sharing a sentence is not in itself a finding about the gene and the disease.
cancer (continued). "Despite these limitations, our study clearly suggests that the high-intensity aerobic exercise resulted in changes in the expression of muscle-derived anticancer genes (Fos, Col1a1, Trim63, and Six2) that may account for the cancer-preventive effect of aerobic exercise." (PMID 35801156, 2022). "Thus we expand our research from gastrointestinal cancers to the pan-cancer analysis of COL1A1." (PMID 34395525, 2021). "However, the expression level, signaling pathway, prognostic prediction, and immunological value of COL1A1 in different cancers remain unclear." (PMID 34395525, 2021). "In the era of precision medicine, it would be exciting to carry out a biomarker-guided basket trial to study the potential role of COL1A1 inhibitors in different cancers, and it might be an optional treatment for patients with advanced tumors, just like pembrolizumab could be used in MSI-H patients." (PMID 34395525, 2021). "Cancer progression can be regulated by deleting a single copy of the phosphate and tension homology deleted on chromosome ten (PTEN) gene or by completely silencing this gene, resulting in the increased recruitment of cancer-associated fibroblasts (CAFs) and production of COL1A1." (PMID 31521169, 2019). "In summary, our investigation into the role of immune-related genes, including COL1A1, ITGB1, THY1, and PDGFRA, in UCEC sheds light on their multifaceted contributions to cancer development and progression." (PMID 40817072, 2025). "Among these, type I collagen (COL1A1) is especially critical, as it promotes EMT, tumorigenesis, metastasis, and resistance to apoptosis and chemotherapy across multiple cancer types." (PMID 41149589, 2025). "To assess the clinical relevance of COL1A1, ITGB1, THY1, and PDGFRA genes in UCEC progression, we examined the correlation between their transcriptional expression levels and cancer stages." (PMID 40817072, 2025). "Previous studies have shown that targeting COL1A1 can modulate PI3K/Akt activity and impact cancer progression." (PMID 40851082, 2025). "When COL1A1, ITGB1, THY1, and PDGFRA are down-regulated, they contribute to a cascade of molecular events that profoundly impact cancer development and progression." (PMID 40817072, 2025). "We thoroughly investigated the biological significance of EDN1/ARRB1 expression with COL1A1 or FN1 by examining their expression levels and predictive value for OS or PFS and SOC cancer staging (stages 1 + 2 or 3 + 4)." (PMID 39985042, 2025). "Analysis of cluster-specific genes indicates that these clusters correspond to cancer cells (GFP, Crabp1, Ank), myeloid cells (Aif1, Ctsc, Mpeg1), lymphoid cells (Il2rb, Cd28, Cd3e/g/d, Cd37), and stromal cells (Col1a1/2, Lum, Eln, Dpt), respectively." (PMID 41280683, 2025). "The integrative analysis identified PROX1+ LEC subsets, JAM2+ BECs, COL1A1+ stromal cells, PTPRC+ leukocytes, including MZB1+ plasmablasts, KRT19+ cancer cells, and MKI67+-proliferating cells." (PMID 41249124, 2025). "Like COL1A1, COL1A2 is involved in various cellular processes, including cell adhesion, migration, and proliferation, making it an important player in cancer biology." (PMID 38913913, 2024). "The non-immune cells included endothelial cells (PVALP and PECAM1), CAFs (COL1A1 and COL1A2), and cancer cells (KRT18 and VEGFA)." (PMID 38216635, 2024). "Previous studies have also reported dysregulation of COL1A1, COL1A2, COL3A1, and FN1 promoter methylation in various cancers." (PMID 38913913, 2024). "Through this analysis, we identified eight major cell types, namely B cell (CD79A), cancer cell (KRT5), cycling cell (MKI67), endothelial cell (VWF), fibroblast (COL1A1), mast cell (KIT), monocyte/macrophage (CD14) and T cell (CD3D)." (PMID 38279519, 2024).
cancer (continued). "Key genes such as COL1A1, COL4A1, PIK3CA, PIK3R1, and mTOR were found to be overexpressed, correlating with increased cancer aggressiveness." (PMID 39850811, 2024). "Our analyzis identified shared markers among the fibroblasts from both carcinoma types, notably DCN, VIM, ACTA2, CXCL12/14, and COL1A1, which were prominent markers, characteristic of these cells." (PMID 39796089, 2024). "COL1A1 and COL1A2 expression changes are utilized to forecast prognosis in a number of cancer types." (PMID 37396945, 2023). "RNA sequencing from the SCANB and TCGA data sets was utilized to assess the expression of COL1A1 and COL1A2 in HER2+ and ER+/PR+ cancers." (PMID 38102637, 2023). "We therefore evaluated the expression of a panel of epithelial (KRT5, 7, 8, 18, and CDH1), mesenchymal (VIM, FN1, SNAI1, TWIST1, COL1A1, and PRRX1), and cancer stem cell (ALDH1A2, ALDH7A1, CD44, and CCND1) markers in all samples." (PMID 36980717, 2023). "Further, COL1A1, COL1A2, COL6A1, COL6A3, and SDC1 were upregulated in late-stage compared with early-stage patients in four cancer types." (PMID 38002057, 2023). "Hsa_circ_0057105 was shown to regulate the expression of COL1A1, a potent EMT regulator in many cancers, through its sponge effect on miR‐577." (PMID 37496319, 2023). "Particularly, the positive correlations of PODNL1 expressions with such collagens as collagen type 1 alpha 1 chain (COL1A1), COL1A2 and collagen type V alpha 1 chain (COL5A1) were found in over 30 types of cancers." (PMID 37504302, 2023). "The “Proteoglycans in cancer” pathway was also exclusively enriched in AA-SScL fibroblasts, driven by the upregulation of IGF2, DCN, LUM, COL1A1, COL1A2, and the receptors KDR and TLR4." (PMID 36835058, 2023). "By comparing the genes (COL1A1, PDL2) involved in cancer cell progression, the expression level of GPR50 was found to be upregulated in CSLC." (PMID 36769125, 2023). "Although, we did not ascertain any significant relationship between the expression of COL1A1 and DFI in LGG patients, it was worth noting that high COL1A1 expression relates to DSS and PFI in multiple cancers including LGG." (PMID 35789341, 2022). "Here, we did not observe a significant difference in the number of CK+/CD45− cancer cells between NSG mice and Col1a1-Krm2-transgenic NSG mice." (PMID 35158823, 2022). "Correlation between the COL1A1 or COL5A1 expressions and CAF infiltration was strong in all four cancers (rho > 0.5)." (PMID 35739492, 2022). "Among them, COL1A1, COL1A2, MT-CYB, CCT5, and PAPPA have been reported to be closely related to cancer." (PMID 35360863, 2022). "RCC tissues that successfully generated organoids highly expressed genes associated with stemness (WNT6/11, FZD8/9 and JAG2), cell matrix (MMP2, COL1A1), fatty metabolism (ACOT2, LIPE) and cancer development (TGFB1, SMAD6/7, EGF and FGF1)." (PMID 35802820, 2022). "CCL2, CRIM1, COL1A1, 6A1, 6A2 participate in cell migration, invasion, or EMT and ABCG2, ALDH1A1, NES are cancer stem‐cell markers." (PMID 36305167, 2022). "Further analysis of the correlation between these key genes and the pathological stage of GC showed that COL1A1, COL5A2, P4HA3, and SPARC were significantly correlated to cancer pathological stages." (PMID 35368700, 2022). "Many studies have shown that SP1 promotes the transcriptional activation of genes and that SP1 and COL1A1 are highly expressed in a variety of cancers, suggesting that SP1 and COL1A1 are positively correlated." (PMID 36360208, 2022). "We identified 25 genes that are highly correlated (rho ≥ 0.5) with both COL1A1 and COL5A1 in all three cancers." (PMID 35739492, 2022). "Risk signature contigs mapped at least five other genes with established driver roles in PCa or other cancers: CAMK2N1, COL1A1, GTSE1 and PTPRN2, supporting the relevance of these sequence contigs in PCa etiology." (PMID 33845808, 2021). "We found that all three genes (SERPINE1, COL1A1, and DKK1) had been reported to be closely related to cancer progression." (PMID 33969120, 2021).
cancer (continued). "This technique identified cell clusters that, through marker genes, included cancer cells—markers EpCAM, KRT8, KRT18, and KRT23, fibroblasts—marker COL1A1 (cancer cells, 4389 cells; fibroblasts, 2549 cells)." (PMID 34026600, 2021). "In our study we have observed up regulation of COL1A1 and down regulation of the canonical Wnt/β-catenin pathway, raising the hypothesis of a possible cross talk between collagens and the canonical Wnt pathway resulting in cancer cell progression to distant organs." (PMID 33670920, 2021). "Among these proteins, the overexpression of MMP14, ITGA2, THBS2, COL1A1, COL3A1, COL11A1 and COL6A3 has been experimentally confirmed in PDAC, while that of COL12A1 and COL5A2 has been shown in other types of cancer." (PMID 34094925, 2021). "ESR1, TOR1AIP1, STAT1, COL1A1 were identified as high expression, while EGFR, AR, GATA2 were identified as a low expression in both cancer types." (PMID 33907495, 2021). "Genes such as COL1A1 and COL3A1, components of collagen fibril are extracellular matrix structural constituent and play important role in cancer invasion and metastasis." (PMID 33663405, 2021). "In order to analyze the correlation between COL1A1 gene expression and prognosis, we used GEPIA2 to analyze the OS and DFS of COL1A1 among different cancers." (PMID 34395525, 2021). "For KEGG pathway enrichment analysis results, microRNAs in cancer, PI3K-Akt signaling pathway, and regulation of actin cytoskeleton were related to high COL1A1 expression." (PMID 33490271, 2021). "As COL1A1 and MMP13 have been reported to be correlated to the metastasis of several types of cancers, GEPIA database was used to confirm the high expression of MMP13 and COL1A1 in TC tissues, showing correlated with TNM stage." (PMID 33014334, 2020). "Cancer generally demonstrates rapid and anomalous growth through extracellular matrix (ECM) remodeling by collagen type I α 1 (COL1A1) and its collagen family members, and the ECM is also highly activated by the Wnt pathway." (PMID 33665169, 2020). "Kaplan–Meier survival analysis showed that the expression levels of COL1A1, COMP, and SERPINE2 significantly correlated with cancer-specific survival and overall survival of BC patients." (PMID 32850407, 2020). "Both COL1A1 and COL1A2 were significantly upregulated in cancer samples compared with normal samples." (PMID 31409759, 2019). "miR-29c-3p expression level was markedly lower but COL1A1 and COL1A2 expression levels were higher in cancer samples than that in normal samples." (PMID 31409759, 2019). "Expression of DUXAP8, DUXAP9, COL1A1 and COL1A2 were significantly increased in cancer samples compared to normal controls while miR-29c-3p expression was decreased." (PMID 31409759, 2019). "Further investigations of the remaining genes such as FN1, EEF1A1, COL1A1, SFTPB, SFTPC, and ATP1A1 will shed light on the identification of novel biomarker genes for a pan-cancer cohort." (PMID 31324856, 2019). "qPCR showed that DUXAP8, DUXAP9, COL1A1 and COL1A2 were significantly upregulated in renal cell carcinoma cancer samples compared with normal controls whereas miR-29c-3p expression in cancer tissues was decreased." (PMID 31409759, 2019). "Two collagen I proteins (COL1A1, COL1A2) were found significantly upregulated in cancer group compared to normal tissue." (PMID 30175151, 2018). "Characteristic fibroblast activation gene targets such as ACTA2, COL1A1 and TNC were significantly upregulated in CAFs together with typical cancer-induced chemokines most prominently CXCL12, which has been reported for this cell line." (PMID 28372546, 2017). "Meanwhile, COL1A1 is a member of collagen family and mainly expressed in the ECM, and collagens are overexpressed in the majority of human cancers." (PMID 28775672, 2017). "We report that all of the studied collagen types (COL1A1, COL3A1, and COL6A1) in the AT, to be modulated by cancer cachexia." (PMID 28288584, 2017).
cancer (continued). "Recently, similar to the expressions of other members of the collagen family which is believed to be involved in carcinogenesis, abnormal expression of COL1A1 and COL1A2 has been reported in several cancers." (PMID 27894325, 2016). "In particular, we show a complex functional cooperation involving IGF-IR, GPER and DDR1 through which IGF-I up-regulates first the expression of COL1A1 and certain DDR1 target genes, thereafter stimulating cancer cell motility and chemotactic response." (PMID 27384677, 2016). "The role of type I collagen, composed of collagen type I alpha 1 (COL1A1) and collagen type I alpha 2 (COL1A2), has been studied in several cancers." (PMID 27894325, 2016). "In the osteoblasts_Gapd2 subpopulation, pathways such as proteoglycans in cancer (Col1a1, Col1a2, Hcls1, Hif1a, Stat3, Vav1), IL-17 signaling (Mmp13, Mmp3, S100a9, Ccl7, Cebpb), and ECM–receptor interaction (Col11a2, Col1a1, Ibsp, and Tnn) were activated (p < 0.05)." (PMID 41459160, 2025). "COL1A1 mRNA expression was significantly elevated in KIRC and several other cancer types." (PMID 40851082, 2025). "However, the expression patterns of COL1A1 and COL1A2 in malignant tumors remain a matter of debate." (PMID 41463322, 2025). "In cancer zone A, cancer cells primarily communicated through the COLLAGEN pathway via ligand–receptor interactions, including Col1a1-(Itga9+Itgb1), Col1a1-Cd44, Col1a2-(Itga9+Itgb1), and Col1a2-Cd44, with Col1a2-(Itga9+Itgb1)/Cd44 showing the strongest interaction strength." (PMID 40723284, 2025). "COL1A1 supports ITGB1 and many other molecules in the invasion and migration of cancer cells." (PMID 38963646, 2025). "Module III represents CAFs expressing COL1A1, COL1A2, and COL3A1 enriched in the cancer regions, whereas module IV identifies a subset known as myofibroblasts (myCAFs) (COL12A1, THBS2) that mainly contribute to extracellular matrix remodeling and growth and metastasis of cancer cells." (PMID 40033360, 2025). "However, this is largely driven by high weightings of three collagen genes; COL1A1, COL3A1 and COL6A3, which steadily increase in inflamed, dysplasia and cancer samples compared to normal tissue samples, with adjusted P-values <0.003." (PMID 38505585, 2024). "Notably, COL1A1 and PLAU are dual targets of zoledronic acid anhydrous, a drug proven in previous experiments to reduce cancer mortality and the incidence of cardiovascular events." (PMID 39712244, 2024). "Once cancer cells arrive in the new soft environment of the lung, they release soft EVs that transform the resident fibroblasts toward a CAF phenotype through increased expression of ACTA2, COL1A1, and VEGFA, VIM." (PMID 38630893, 2024). "In addition, pan-dCAFs expressed high levels of COL11A1, COL1A1, MMP11 and MMP1, which are closely related to cancer invasion." (PMID 38827236, 2024). "Additionally, the protein-protein interaction network analysis in this study revealed an interaction between COL1A1 and MMP12, suggesting a potential functional connection between these two genes in the context of cancer progression." (PMID 39124881, 2024). "Gene expression analysis across all three cancer types subsequently found a common increase in the expression of five genes (BCAR1, COL1A1, IGSF3, RRAD, and TFPI2), which may further inform biomarker study for identifying CTCs." (PMID 36980717, 2023). "Excessive COL1A1 accumulation in the ECM can lead to various diseases, including cancer." (PMID 37393249, 2023). "TS-C2 was located between cancer cells and islets and expressed FNDC1 and COL1A1." (PMID 37124494, 2023). "DMBA-induced mammary gland carcinoma as marked by an elevation of mRNA level of cancer promoter genes (Serpin and MIF, LOX-1, and COL1A1) and serum level of VEGF, TNF-α, TGF-β, CA15-3, and caspase-3 with the reduction in mRNA level of suppressor gene (FST and ADRP)." (PMID 35138531, 2023).
cancer (continued). "In the ground of methylation, one hyper-methylated/under-expressed gene (CA12) and two hypo-methylated/over-expressed genes (COL1A1, and TACSTD2) were found which were confirmed both by expression (only by the validation dataset) and methylation (by MEXPRESS in two COAD, and READ cancer types)." (PMID 35333898, 2022). "Col1a1 is related to the PI3K-AKT pathway and proteoglycans in cancer signaling pathways." (PMID 35801156, 2022). "Identifying the players for the opposing roles of COL1A1 and COL5A1 in different cancers could reveal new insights into the field." (PMID 35739492, 2022). "Collectively, these results suggest tumoral mRNA expression of MMP1, MMP9, COL1A1 and LAIR1 significantly impacts survival of cancer patients, and therefore led to the hypothesis that MMP generated collagen I fragments might activate LAIR-1." (PMID 34691040, 2021). "Unlike control cells, cancer cells knocked down for COL1A1 no longer respond to the increase in stromal-cell-derived collagen caused by lenti-BMP1." (PMID 33879793, 2021). "Significant focal amplifications and deletions, identified by GISTIC2, were evident in regions with known cancer genes, for example, significant focal Cdkn2a deletions (GISTIC q value = 1.39 × 10−5) were evident and EGFRvIII (in Col1a1 locus, GISTIC q value = 0.017) was recurrently amplified." (PMID 32727536, 2020). "Moreover, in 1019 cancer cell lines, there were positive correlation between ASPH and RUNX2 or COL1A1." (PMID 33015050, 2020). "Furthermore, the focal adhesion genes such as COL1A1, COL10A1, and COL11A1 were also found to be up-regulated in the present study and are also reported to be up-regulated in various cancers including breast tumours." (PMID 31292488, 2019). "Furthermore, H19 regulated many other cancer-related genes in this network, such as AKT3, CSF1, MET, COL1A1, COL5A1, WWTR1, EPHB4, and TMPRSS3." (PMID 31164794, 2019). "The COL1A1-PDGFB fusion gene is detected in >90 % of cases of DFSP and represents a very useful tool for the differential diagnosis of DFSP with other benign/malignant neoplasms." (PMID 26932148, 2016). "However, while treatment of luminal cancer cell lines with recombinant TGFβ (rTGFβ) increased FN1 and COL1A1 expression, the magnitude of the effect was smaller, and a longer treatment was needed in cells with high endogenous ThPOK levels (T47D), compared to cells with lower levels (MCF7)." (PMID 41231242, 2025). "A grouping of higher fibroblast signal is seen in a subset of cancer/dysplasia samples, and excludes normal tissue, which might be driven by the collagen gene COL1A1, which has the highest fibroblast weighting in the reference matrix." (PMID 38505585, 2024). "The genome-wide co-expression analyses showed that the expression levels of collagen genes (COL1A1, COL1A2, COL5A1, COL5A2, COL8A1 and COL8A2) and LincRNAs (Linc01614 and Linc01711) were significantly positively correlated with PODNL1 expressions in various cancers." (PMID 37504302, 2023). "The significantly overexpressed sEV proteins in the BC plasma-derived UCT isolates were ALB, COL1A1, CSN1S1, EEF1A2, and RPL3; and the C1S, C5, C7, and CFHR2 sEV proteins in the UCT isolates were the most downregulated proteins in the BC plasma compared to the non-cancer control." (PMID 37895140, 2023). "COL1A1 is regulated by MRTF-A in the Wnt/β-catenin-induction, which integrates signals from various pathways to control the Type I collagen synthesis, reciprocally stimulating the signal transduction in cancer cells—besides promoting metastasis and proliferation." (PMID 35159353, 2022). "However, most cancers showed THY1 and COL1A1 hypomethylation compared to normal samples." (PMID 36032075, 2022).